NAXE (NAD(P)HX epimerase)
Description:
Catalyzes the epimerization of the S- and R-forms of NAD(P)HX, a damaged form of NAD(P)H that is a result of enzymatic or heat-dependent hydration (By similarity). This is a prerequisite for the S-specific NAD(P)H-hydrate dehydratase to allow the repair of both epimers of NAD(P)HX (By similarity). Accelerates cholesterol efflux from endothelial cells to high-density lipoprotein (HDL) and thereby regulates angiogenesis.
Synonyms: AIBP; APOA1BP; YJEFN1; MGC119143; MGC119144; MGC119145; PEBEL
Tractability: Antibody: UniProt places it where antibodies can reach, with high confidence; its Gene Ontology location is reachable by antibodies, with high confidence. PROTAC: ubiquitination databases record sites on it.
Gene: Protein-coding gene on chromosome 1 (156,591,743 to 156,609,507, forward strand). Ensembl gene ENSG00000163382.
Subcellular location: Mitochondrion; Secreted
Subcellular location (Human Protein Atlas): Nucleoplasm; Cytosol; Vesicles; Predicted to be secreted
Pathways (Reactome):
Metabolism: Nicotinate metabolism
Gene Ontology:
Molecular function: NAD(P)HX epimerase activity; protein binding; identical protein binding
Biological process: membrane raft distribution; negative regulation of angiogenesis; nicotinamide nucleotide metabolic process; regulation of cholesterol efflux; sprouting angiogenesis; metabolite repair
Cellular component: extracellular exosome; extracellular region; mitochondrion; mitochondrial matrix; cell body; cilium; cytosol
Genetic constraint (gnomAD): Loss-of-function variants: 25 observed, 32.35 expected, observed/expected ratio (o/e) 0.77, 90% interval 0.56 to 1.08. The upper end of that interval is the gene's LOEUF score, 1.08, which puts it in group 4 of 6, group 1 being the genes least tolerant of losing a copy. Missense variants: 362 observed, 391.6 expected, observed/expected ratio (o/e) 0.92, 90% interval 0.85 to 1.01. Synonymous variants: 144 observed, 160.02 expected, observed/expected ratio (o/e) 0.9, 90% interval 0.79 to 1.03.
Gene-disease validity (ClinGen):
ClinGen rates the evidence that NAXE causes each of these diseases.
mitochondrial disease (autosomal recessive): Definitive.
Leigh syndrome (autosomal recessive): Limited. A progressive neurological disease defined by specific neuropathological features associating brainstem and basal ganglia lesions.
Homologues: Orthologues: chimpanzee NAXE (99% identical), macaque NAXE (96% identical), rabbit NAXE (91% identical), pig NAXE (91% identical), rat Naxe (88% identical), mouse Naxe (88% identical), dog NAXE (88% identical), guinea pig NAXE (86% identical), zebrafish naxe (68% identical), tropical clawed frog naxe (68% identical), Drosophila melanogaster Naxe (49% identical), Caenorhabditis elegans Y18D10A.3 (38% identical). Paralogues in human: YJEFN3 (42% identical).
Diseases named in the same sentence as NAXE in open-access papers:
NAXE is named in the same sentence as 26 diseases in open-access papers, as found by Europe PMC text mining. Sharing a sentence is not in itself a finding about the gene and the disease. The quoted sentences say what the papers report.
atherosclerosis (3 papers, 2022 to 2025). A disease characterized by the build-up of fatty material and calcium deposition in the arterial wall resulting in partial or complete occlusion of the arterial lumen. "The pathologies associated with these NAXE-orchestrated functions include atherosclerosis and retinal neuronal dysfunction." (PMID 36429071, 2022).
brain edema (3 papers, 2021 to 2025). Increased intracellular or extracellular fluid in brain tissue. "Pathogenic NAXE variants are associated with PEBEL (encephalopathy, progressive, early-onset, with brain edema and/or leukoencephalopathy) (OMIM #617,186)." (PMID 39026379, 2024).
Encephalopathy (3 papers, 2021 to 2026). Encephalopathy is a term that means brain disease, damage, or malfunction. "Given the unexplained encephalopathy, whole-exome sequencing was performed, which identified compound heterozygous NAXE mutations, confirming the diagnosis." (PMID 41737236, 2026). "This case report presents a case of NAXE gene mutation who presented with encephalopathy with a fluctuating disease course." (PMID 34678889, 2021). "Although NAXE gene mutation-related encephalopathy is rare, it should be considered as a differential diagnosis of early onset progressive encephalopathy." (PMID 34678889, 2021). "NAXE gene mutation-related encephalopathy is usually regarded as a lethal neurometabolic disorder." (PMID 34678889, 2021).
edema (1 paper, 2021). An abnormal accumulation of fluid beneath the skin, or in one or more cavities of the body. "Progressive encephalopathy with brain edema and/or leukoencephalopathy-1 is an infantile, lethal neurometabolic disorder caused by a NAD(P)HX epimerase (NAXE) gene mutation." (PMID 34678889, 2021). "Progressive encephalopathy with brain edema and/or leukoencephalopathy-1 (PEBEL-1) is a rare metabolic and autosomal recessive disorder that results from a NAD(P)HX epimerase (NAXE) gene mutation." (PMID 34678889, 2021).
glaucoma (1 paper, 2024). Increased pressure in the eyeball due to obstruction of the outflow of aqueous humor. "We have reviewed the proposed functions of AIBP in protecting against the development of glaucoma, from inhibition of TLR-mediated inflammation via disruption of TLR4-associated lipid rafts to the regulation of mitochondrial function to NAXE activity." (PMID 38275823, 2024).
hyperlipidemia (1 paper, 2022). "Consistent with this hypothesis, NAXE LOF mutation in zebrafish contributes to mild hyperlipidemia and lipid deposition in cardiac tissue." (PMID 36429071, 2022).
NAXE also shares sentences with these, for which no sentence is quoted: Leukoencephalopathy (2 papers); migraine (2); Alzheimer disease (1); Ataxia (1); brain tumors (1); cardiovascular disease (1); cholesterol metabolism disorders (1); cognitive decline (1); Cognitive impairment (1); COVID-19 (1); encephalopathy, progressive, early-onset, with brain edema and/or leukoencephalopathy (1); gastric disease (1); intestinal tumors (1); Mitochondrial myopathy (1); pediatric cancers (1); pellagra- (1); peripheral neuropathy (1); Progressive encephalopathy (1); psychiatric disorder (1); schizophrenia (1).